RNU6-836P (RNA, U6 small nuclear 836, pseudogene)
Gene: Small nuclear RNA gene on chromosome 4 (41,084,607 to 41,084,713, forward strand). Ensembl gene ENSG00000199790.
Homologues: Orthologues: chimpanzee U6 (99% identical), macaque U6 (92% identical), rabbit U6 (82% identical). Paralogues in human: RNU6-1145P (90% identical), RNU6-16P (90% identical), RNU6-38P (90% identical), RNU6-393P (90% identical), RNU6-46P (90% identical), RNU6-639P (90% identical), RNU6-1099P (89% identical), RNU6-1316P (89% identical), RNU6-144P (89% identical), RNU6-20P (89% identical), RNU6-211P (89% identical), RNU6-29P (89% identical), and 1287 more.